NRG1 (neuregulin 1)
Diseases named in the same sentence as NRG1 in open-access papers (continued):
Sharing a sentence is not in itself a finding about the gene and the disease.
cancer (continued). "Neuregulin-1 (NRG-1) belongs to the neuregulin family, which was first discovered and studied in neural and cancer cells." (PMID 32765805, 2020). "From our top 10 specific TFs, only 3 are differently expressed in this cancer type (PLXNB2, NRG1, SAP30BP)." (PMID 33057419, 2020). "GSEA revealed that the DE-ATGs in the high ITGA3, MAP1LC3A, and NRG1 expression groups in the TCGA GBM cohort were mainly enriched in KEGG pathways related to autophagy and cancer." (PMID 31844032, 2019). "With 10 DEG each, 2 biological processes were modulated, cellular responses to external stimuli with genes coding for prostaglandin protein, histone cluster, and heat shock protein and disease with NAG20, NRG1, SLA2, CSNK1A1L (signalling by WNT in cancer)." (PMID 31797963, 2019). "Interestingly, we also observed that ErbB3 was also rarely overexpressed in squamous lung cancer samples (unpublished observations), suggesting that ErbB3 signaling in cancers of squamous origin, which often express NRG1, may lead to downregulation of ErbB3 mRNA expression." (PMID 28723928, 2017). "More importantly, treatment of cancer cells with an anti-HER3 monoclonal antibody (HER3Mab) effectively neutralized the elevated pHER3 and pAKT levels induced by NRG-1 in high DJ-1 expressing and control (pCDNA) cancer cells." (PMID 27582551, 2016). "Compared with empty-vector control (e.v.)and SLC3A2, cancer cells expressing NRG1 and SLC3A2-NRG1 fusion genes showed substantial enhancement." (PMID 27626312, 2016). "As expected, DJ-1 knockdown cells also showed a reduced response to NRG-1 stimulation of cell proliferation, 122 % and 131% increase in DJ-1 knockdown cells vs. 136% and 146% in shScramble control for T47D and MCF-7 cancer cells, respectively." (PMID 27582551, 2016). "Taken together, these data suggest that activation of HER3 by NRG-1 triggers the dissociation of HER3 and DJ-1 in cancer cells." (PMID 27582551, 2016). "Nrg1 is one of the most active members of the epidermal growth factor (EGF)-like family, and also is considered to be a cancer related cytokine." (PMID 25560389, 2015). "The optimal detection methods and clinicopathological features of patients with NRG1 fusion-positive cancer have not been systematically studied." (PMID 41390931, 2026). "In the case of no access to RNA sequencing, NRG1 FISH consists of a valuable tool searching for NRG1 fusions in patients with advanced cancers." (PMID 40723230, 2025). "Specifically, previous studies with engineered bivalent NRG1 that activates the ERBB system by forced ERBB4 homodimerization, reproduced the anti-apoptotic effects of NRG1 in cardiomyocytes, without inducing growth of cancer cells." (PMID 39794341, 2025). "To further explore whether the effects of NRG1 on BC cells are mediated by the AKT/mTOR pathway, we utilized the AKT inhibitor ARQ751 trihydrochloride to suppress AKT/mTOR signaling in cancer cells." (PMID 41213930, 2025). "It targets NRG1 fusions by binding to both HER2 and HER3 on the surface of cancer and immune cells." (PMID 41179283, 2025). "The SLC3A2-NRG1 fusion protein is composed of a SLC3A2 (SLC3A2 heavy chain) transmembrane domain and the EGF-like domain of the neuregulin 1(NRG1) protein (NRG1 III-β3 form) which its overexpression has been seen in cancer progression." (PMID 38705513, 2024). "The discovery of gene fusions involving Neuregulin-1 (NRG1) within solid tumors has important therapeutic implications, as they are being actively explored as targets for emerging ERBB/ERBB2/ERBB3-directed anti-cancer agents." (PMID 39575425, 2024). "Cancer therapies targeting ERBB3 are known to be cardiotoxic, while its ligand NRG1 may improve LVventricular contractility in HFrEF." (PMID 39180332, 2024). "NRG1 and the ERBB receptors are important clinical target in different cancer types." (PMID 39210279, 2024).
cancer (continued). "Taken together, NRG1–ERBB/HER signaling is critically important for neuronal progenitor proliferation, survival, maturation, and synapse formation, but is also multifunctional, and particularly important in cancer." (PMID 38369520, 2024). "Moreover, numerous oncogenic drivers (ALK, BRAF, EGFR, MET, NRG1, NTRK1/2/3, RET, and ROS1) involved in sole reciprocal fusions were found in those cancers." (PMID 39254060, 2024). "When patients with cancer are given pan-ERBB/HER inhibitors, ERBB4/HER4/ALS19 function is attenuated, but any feedback upregulation of NRG1 should it occur cannot overstimulate ERBB1/2/3 because the pan-ERBB/HER inhibitor diminishes the function of these other ERBBs." (PMID 38369520, 2024). "To address whether the improved survival observed in CRC with high NRG1 mRNA levels relates to stromal expression, we scored 315 CRC patients' tissue microarrays for NRG1 expression separately in cancer (epithelial) and in stromal cells." (PMID 36912192, 2023). "On the contrary, decreased levels of neuregulin 1 (NRG1), a direct ligand of ERBB3 and ERBB4 tyrosine kinase receptors, which activate ERBB receptors, could be responsible for the inhibition of cancer cell growth." (PMID 37834191, 2023). "CTGF and CYR61 are both known to enhance anchorage-independent growth of cancer cells, thus these YAP downstream genes might be involved in the action of NRG1/HER3/YAP axis to regulate anchorage-independent growth of AM cells." (PMID 36765036, 2023). "Interestingly, the activation of ERBB4 by ligands (NRG1, HBEGF) has been shown to inhibit proliferation and/or promote differentiation in human breast normal and cancer cell lines." (PMID 35664762, 2022). "In support of this hypothesis, all affected proteins predicted on the basis of our mCRC‐specific deregulated miRNA dataset, most significantly NRG1 and CXCL12, are part of the pathways involved in cancer signalling and stem cell pluripotency." (PMID 34288395, 2021). "This indicates that CAF-secreted NRG1 positively contributes to proliferation of cancer cells while it does not affect CAFs." (PMID 33692466, 2021). "We identified HBV integrations with high integration allele fractions in tumors in seven non-recurrent cancer-related genes, including GAS7, NSP, RSPO2, NRG1, PRDM16, ARID1B, and AFF1." (PMID 33557409, 2021). "To investigate the clinical significance of the HER3 pathway in SCCHN, we first evaluated the expression status of HER3 and its ligand NRG1 in 100 cases of OSCC, which is the 4th leading cancer type in the male population in Taiwan, through immunohistochemical staining." (PMID 34465724, 2021). "To test this, we added ectopic NRG1 to cancer cells that had or had not been pre-incubated with either lumretuzumab or pertuzumab." (PMID 33692466, 2021). "Due to the established role of NRG1 in epithelial to mesenchymal transition (EMT) and migration processes, we next measured if also migration abilities of the cancer cells were altered in presence of CAF-CM and if these were dependent on HER3 activation by NRG1." (PMID 33692466, 2021). "NRG1 fusions occur in ~ 3% NSCLC, ~ 1.5% pancreatic cancer and less than 1% of other cancers, and are detected frequently in KRAS–wildtype pancreatic ductal adenocarcinomas (PDAC) providing a potential drug target for those patients who do not benefit from KRAS inhibitors." (PMID 32989604, 2020). "These sub-networks showed the interactions between paracrine factors and their receptors including TNF-TNFR, NRG1-EGFR (ERBB), and WNT-FZD further indicated that paracrine factors TNF, NRG1, and WNT from infiltrated dendritic cells were involved in cancer pain." (PMID 32434423, 2020). "Indeed, NRG-1, PSEN1 and ERBB4 dysfunction have been described as key contributors in the pathogenesis of cancer, cardiovascular disease, and neurological disorders." (PMID 31396490, 2019).
cancer (continued). "NRG1 is a direct transcriptional target gene of NUP98 and functions along with its receptor ERBB4 in various normal and pathological conditions including cardiac development, cancer and neurodegeneration diseases, etc.." (PMID 31396490, 2019). "To precisely determine the underlying molecular mechanisms, we assessed apoptosis induction in three cancer cell lines at different time points during incubation with the allosteric NRG1 non-competing antibody 9F7-F11." (PMID 31443721, 2019). "Several studies found that activation of YAP enhances the downstream gene expression of EGFR ligands such as Amphiregulin (AREG) and Neuregulin 1 (NRG-1), and ERBB3 and ERBB4, to form an autocrine loop and reinforce the MAPK signaling pathway to induce cancer progression and drug resistance." (PMID 31387256, 2019). "In this respect, it is worthwhile noticing that inclusion of Neuregulin-1 in the medium is probably not the answer to specific growth requirements of cancer cells." (PMID 31829259, 2019). "The results in this study showed HER3 activation upon HER2Mab treatment in both MCF7 (low HER2) and MCF7-HER2 (high HER2) cancer cells independent of the HER3 ligand NRG1, and HER3 activation is a result of HER3/EGFR dimerization." (PMID 23342251, 2012). "However, owing to the limited number of patients with NRG1 fusions across each cancer type, our study did not investigate the impact of NRG1 fusions on prognosis within specific cancer types." (PMID 40730881, 2025). "Hence, NSCLC patients harboring NRG1 fusions may benefit from targeted therapies such as pan-HER family inhibitors, which have shown efficacy in previous studies in various cancers, and anti-HER monoclonal antibodies." (PMID 39123493, 2024). "Additionally, NRG1 overexpression predicted poor outcome in hyperglycemic HER2-positive cancer patients but not in HER2-negative patients." (PMID 36707514, 2023). "In addition, our study did not evaluate the potential role of NRG1 directly produced by cancer cells." (PMID 35406375, 2022). "The strongest effect was observed for CAF#3-CM, the CAF culture that expressed the highest level of NRG1.Treament with lumretuzumab of cancer cells cultured in control media, did not alter their migration abilities, confirming the absence of an autocrine HER3 activation." (PMID 33692466, 2021). "To ascertain whether different expression of NRG1 by CAFs translates into variable activation of the HER3 pathway in cancer cells, we stimulated T47D and MCF7 cancer cells with conditioned media (CM) from the isolated CAFs, and used lumretuzumab to block ligand–receptor binding." (PMID 33692466, 2021). "Similarly, shDJ-1 T47-D and shDJ-1 MCF-7 cancer cells also showed reduced cell migration in the presence and absence of NRG-1 stimulation." (PMID 27582551, 2016). "While the relationship between NRG1 expression and outcome in primary HNSCC has not been reported to our knowledge, elevated expression of ErbB3, a possible surrogate for activity, has been associated with a poor prognosis in a variety of cancer types." (PMID 25238142, 2014). "In addition, fusions of the NRG1 gene with various partner genes, such as the CD74 molecule, solute carrier family 3 member 2, and unc-5 netrin receptor D, have been identified in a wide range of cancer types, although their frequency is low with only 82 such examples out of 44,570 tumors (0.2%)." (PMID 34068503, 2021). "To determine whether ITCH-induced c-FLIPL degradation had a major role in anti-HER3 antibody-induced cancer cell apoptosis, we assessed PARP and caspase-8/3 cleavage by western blotting in siITCH and siSC BxPC3 cells incubated with 9F7-F11 alone or with NRG1 for 48 h." (PMID 31443721, 2019). "HG-induced Nrg1 overexpression was abolished by silencing of P300, Cbp, and Setd1A genes in Met1 cancer cells compared with scrambled (Scrb) shRNA or shRNA non-treated control cells, indicating that P300, CBP, and SETD1A may be associated with Nrg1 enhanceosome assembly." (PMID 36707514, 2023).
cancer (continued). "As expected, NRG-1 increased pHER3 levels in DJ-1 overexpressing T47-D and MCF-7 cancer cells, but had no impact on total AKT and ERK1/2 levels." (PMID 27582551, 2016). "Not surprisingly, HER2/HER3 dimers are abundant in the HER2 overexpressing MCF7-HER2 cells in the absence of NRG1 and this is consistent with previous report that ligand-independent HER2/HER3 dimerization occurs in high HER2 expressing cancer cells." (PMID 23342251, 2012). "Moreover, for some cancers, such as PDADK, molecular testing is not systematically performed, limiting the diagnosis of targetable molecular events, such as NRG1 fusions." (PMID 40723230, 2025). "Thus, in this study, we intend to evaluate the value of NRG1 fusion diagnosis using FISH in a case series of PDADK and LADK, with a focus on cancers with no other identified molecular oncogenic driver." (PMID 40723230, 2025). "In line with the LCM patient data, NRG1 was expressed by all CAF lines, while no expression could be detected in cancer cells." (PMID 33692466, 2021). "Third, NRG1 is a non-selective agonist of the ERBB system, binding to both ERBB3 and ERBB4 receptors, and thus it may activate ERBB3 receptors in ERBB2-overexpressing tumor cells, thereby enhancing the formation of ERBB3/ERBB2 complexes, which could induce or accelerate cancer growth." (PMID 39794341, 2025).
psychiatric disorder (33 papers, 2010 to 2024). A disorder characterized by behavioral and/or psychological abnormalities, often accompanied by physical symptoms. "KLK8 is also known to cleave the extracellular portion of several membrane proteins, including synaptic adhesion molecule L1, neuregulin-1, and ephrin type-B receptor 2, which has been implicated in the pathogenesis of psychiatric disorders." (PMID 37076499, 2023). "Our conclusions fit also to recent investigations in cortical slice preparations from mouse models for psychiatric disorders caused by mutations of genes encoding the Lysophosphatidic acid 1 receptor, neuregulin-1 or ErbB4 receptor." (PMID 25735038, 2015). "The NRG1/ErbB4 signal also involves VIP interneurons in the mPFC, and NRG1 is gaining attention as a therapeutic target for psychiatric disorders." (PMID 35601531, 2022). "Further studies revealed that NRG1-ErbB4 signaling pathway regulates expression of NMDA, GABA, and ACh receptors, which are genetically linked to psychiatric disorders." (PMID 34484386, 2021). "As such, this approach provides a powerful new tool for exploring the multifactorial basis for psychiatric disorders involving NRG1 dysfunction." (PMID 29844389, 2018). "While the small sample sizes we used is a great limitation, this study is novel in that we examined levels of NRG1 cleavage enzymes and levels of NRG1 protein in two psychiatric disorders and two distinct brain regions." (PMID 22590542, 2012). "Thus, neuropathological implication of hyper NRG1 signaling in psychiatric diseases should be evaluated with further experimentation." (PMID 21151609, 2010). "Therefore, together with findings as described in this review, it is possible that juvenile social experience-dependent myelination occurs through the expression of well-known risk molecules for psychiatric disorders, NRG1 and BDNF, and results in the development of psychiatric disorders." (PMID 26078885, 2015). "GSK3B, BDNF, NGF, NRG1, HTR2C, and PIP4K2A play important roles in molecular mechanisms of psychiatric disorders." (PMID 33193575, 2020). "Furthermore, several studies have shown that NRG1, NRG2, or genes of the NRG–ErbB network contribute to the etiology of psychiatric disorders." (PMID 38791584, 2024). "GSK3B, BDNF, NGF, NRG1, HTR2C, and PIP4K2A are genes that showed some importance in the study of the molecular etiology of psychiatric disorders." (PMID 33193575, 2020). "NRG1/erb-b2 receptor tyrosine kinase 4 (ERBB4) signaling in DA-ergic axonal projections modulates DA homeostasis, whereas NRG1/ERBB4 signaling in both GABA-ergic interneurons and DA neurons in the midbrain contribute to the modulation of animal behaviors relevant to psychiatric disorders." (PMID 34072341, 2021).
infection (20 papers, 2011 to 2025). The state of being infected such as from the introduction of a foreign agent such as serum, vaccine, antigenic substance or organism. "Our study also demonstrates the ability of NRG-1/ErbB4 signaling to rescue infection-induced neuropathology in the form of GLT-1 loss via exogenous NRG-1 treatment during Toxoplasma infection, a neuroprotective mechanism that has not been reported previously." (PMID 39095837, 2024). "Previous studies have reported similar results: tet-NRG1 yeast, which are avirulent in immunocompetent mice, can cause lethal infection in immunosuppressed mice." (PMID 34162849, 2021). "Constitutive expression of NRG1 from a heterologous promoter blocks filament formation in vitro and during infection." (PMID 38949302, 2024). "Innate macrophages and CNS-resident microglia also expressed these molecules while adaptive T cells did not express ErbB4 at any time point; however, a subpopulation of T cells (10–20%) did express NRG-1 which increased over the course of infection." (PMID 39095837, 2024). "They achieved this by placing the negative regulator of the filamentation gene; nrg1 under the control of a tetracycline regulatable promoter and found that mice injected with this strain succumbed to infection, while the control did not62." (PMID 37468600, 2023). "The reduced inflammatory response of the host was accompanied by a delay in fungal clearance which manifested by elevated fungal loads on day 3 post-infection in case of the NRG1-overexpressing C. albicans strain in comparison to all controls." (PMID 35404986, 2022). "Mice challenged intravenously with the tet-NRG1 strain succumbed to infection when hyphal growth was permitted but survived when fungal cells were enforced to grow in the yeast form." (PMID 34162849, 2021). "The results showed that Nup98, Nrg1, and erbB4 were upregulated during the acute phase of infection (7 dpi) and decreased at the chronic phase of infection (40 dpi) even though the extent of decrease for Nup98 expression was small." (PMID 31396490, 2019). "Circulating blood NRG-1 level significantly increased in mice 6 days post infection and declined to a level below that of uninfected mice (controls) 8 days post infection when fatal brain damage occurred." (PMID 29636063, 2018). "In line with this, knockdown of Sp1 prior to infection prevented HCV-mediated up-regulation of NRG1 expression suggesting that HCV Sp1-dependently mediates increased production of NRG1." (PMID 26886748, 2016). "Our transcriptional data show an up-regulation of NRG1 in eed1Δ during both, infection of RHE and growth on plastic, and this up-regulation was reversed by ectopic overexpression of UME6 in eed1Δ." (PMID 21512583, 2011). "Here, we show that Nrg1, a key repressor of filamentation and filament specific gene expression in standard reference strains, has strain-dependent functions, particularly during infection." (PMID 38376205, 2024). "Thus, the function of the conserved repressor NRG1 in C. albicans shows strain-based heterogeneity during infection." (PMID 38376205, 2024). "Notably, the enhanced inflammatory response triggered by 101nrg1Δ/NRG1 in the host impaired fungal colonization and resulted in a reduced fungal load on day 7 post-infection." (PMID 35404986, 2022). "However, ERBB4, the receptor of NRG1, had a slight decrease at early time-point of infection and decreased dramatically at 7 hpi." (PMID 31396490, 2019). "Interestingly, NRG1 expression levels during infection were significantly lower in siNUP98 treated cells than in scrambled siRNA treated cells (lane 6–8 vs. 2–4), particularly at 7 hpi, the decrease is ~20-fold (lane 4 vs. 8)." (PMID 31396490, 2019). "Moreover, we found that cleavage of NUP98 leads to the downregulation of cardioprotective genes Nrg1 and erbB4 in later phase of infection." (PMID 31396490, 2019). "The cause of increased expression of NRG-1 including blood NRG-1 levels after PbA infection is not clear." (PMID 29636063, 2018).